TSIX (TSIX transcript, XIST antisense RNA)
Synonyms: NCRNA00013; XIST-AS1; LINC00013; XIST-AS; XISTAS
Gene: Long non-coding RNA gene on chromosome X (73,792,205 to 73,829,231, forward strand). Ensembl gene ENSG00000270641.
Diseases named in the same sentence as TSIX in open-access papers:
TSIX is named in the same sentence as 13 diseases in open-access papers, as found by Europe PMC text mining. Sharing a sentence is not in itself a finding about the gene and the disease. The quoted sentences say what the papers report.
breast carcinoma (4 papers, 2019 to 2025). "TSIX was also among the downregulated lncRNAs in circulating NK cells isolated from peripheral blood of breast cancer patients with fold change 0.05, P = 0.0037." (PMID 40781182, 2025). "Downregulation of TSIX suggests that circulating NK cells in breast cancer patients have dysregulated XIC compared to healthy controls." (PMID 40781182, 2025). "LncRNA XIST and TSIX are pivotal elements in X chromosome inactivation (XCI) as well as breast cancer." (PMID 36810034, 2023). "XIST and TSIX are overexpressed in the lymph nodes, and different body fluids of breast cancer patients but differentially expressed in patients with different breast cancer subtypes." (PMID 34496886, 2021). "XIST and TSIX are two long non-coding (lnc)RNAs possessing a role in X chromosome inactivation (XCI) as well as in breast cancer (BC)." (PMID 31998636, 2019). "Furthermore, lncRNAs XIST and TSIX were markedly increased in the tissues, lymph nodes, and different body fluids of breast cancer patients compared to controls." (PMID 31998636, 2019). "LncRNAs XIST, TSIX, GATA3-AS1 and LINK-A play an oncogenic role in tumor progression and immune evasion in breast cancer and are all notably upregulated in breast cancer tissues, which is related to the expression of PD-L1." (PMID 34496886, 2021).
colorectal cancer (1 paper, 2025). A primary or metastatic malignant neoplasm that affects the colon or rectum. "The univariable analysis showed that increased levels of CA19-9, XIST, and FOXK1, as well as decreased levels of TSIX and miRNA-497, were linked to a greater risk of colorectal cancer (CRC)." (PMID 40032945, 2025).
gastric cancer (1 paper, 2023). A primary or metastatic malignant neoplasm involving the stomach. "In our study, we introduced a potential signature model for gastric cancer survival prediction, including THBS2, BAIAP2-AS1, LINC01215, and TSIX." (PMID 38162289, 2023).
Graves disease (1 paper, 2025). Graves' disease is an autoimmune disorder that leads to overactivity of the thyroid gland (hyperthyroidism).It is caused by an abnormal immune system response that causes the thyroid gland to produce too much thyroid hormones. "XIST, PPP1R2C, CALHM6, AL672277.1, TSIX, SHROOM1, ADTRP, JUND, SGK1, CHKA, AO008569.1, MAP7D2, and AIF1 were down-expressed genes in TS compared with both the healthy female and the female patient with Graves’ disease." (PMID 39851522, 2025).
lung carcinoma (1 paper, 2020). "Leveraging the available large-scale sequence data from TCGA and GTEX, we demonstrate that XIST, TSIX, hnRNPu, Bcl-2, and BRCA1 are differentially expressed in two different types of lung cancer when compared to controls." (PMID 33255394, 2020). "The expression of XIST and co-regulated genes TSIX, hnRNPu, Bcl-2, and BRCA1 analyses in lung cancer (LC) and controls were performed in silico." (PMID 33255394, 2020).
ovarian carcinoma (1 paper, 2024). A malignant neoplasm originating from the surface ovarian epithelium. "However, there are no reports of ovarian cancers expressing CBR3‐AS1, LINC00887, and TSIX; this is the first report of their expression in ovarian cancers, including HGSC." (PMID 38571514, 2024).
systemic sclerosis (1 paper, 2018). A chronic disorder, possibly autoimmune, marked by excessive production of collagen which results in hardening and thickening of body tissues. "TSIX was overexpressed in systemic sclerosis (SSc) dermal fibroblasts both in vivo and in vitro, and is higher in SSc sera." (PMID 29996948, 2018).
cancer (6 papers, 2020 to 2025). A tumor composed of atypical neoplastic, often pleomorphic cells that invade other tissues. "The lncRNAs XIST, TTN-AS1, STRA6LP, and TSIX had high numbers of mutations in most cancers, which play an important role in the oncogenic mechanism." (PMID 34079798, 2021). "In this study we found that differentially expressed levels of mRNAs were related to both testis development and known cancer pathways, as well as the lncRNA, TSIX which exhibited increased levels in TGCT patients." (PMID 33251139, 2020). "However, TSIX has also been shown to synergistically regulate, together with other lncRNAs, cancer genes and pathways across multiple tumor contexts." (PMID 33919332, 2021). "Given the epigenetic mechanisms of gene regulation that TSIX and XIST play in immune cells, their dysregulation can affect NK cell activities in cancer patients, such as NK cell cytotoxicity and cytokine release." (PMID 40781182, 2025).
tumor (5 papers, 2019 to 2021). "This was consistent with previous reports in which lncRNA XIST was shown to act as a tumor suppressor in BC and with the fact that lncRNA TSIX is a negative regulator of lncRNA XIST." (PMID 31998636, 2019). "Clustering of tumour and healthy lung samples in a 2D map using t-SNE algorithm based on the normalized expression levels of XIST, TSIX, hnRNPu, Bcl-2, and BRCA1, revealed that collectively these five genes -when assessed together- can have a diagnostic potential in both LUAD and LUSC." (PMID 33255394, 2020). "Nonetheless, limited evidence displayed lncRNA XIST involvement as a tumor suppressor lncRNA in BC in addition to the absence of concerns regarding lncRNA TSIX, the negative regulator of lncRNA XIST in BC." (PMID 31998636, 2019). "As for the contribution of lncRNAs XIST and TSIX in BC, their precise role is largely unknown with minimal studies reporting lncRNA XIST as a tumor suppressor lncRNA whose level is downregulated in BC, with no suggestions about lncRNA TSIX role in BC." (PMID 31998636, 2019).
TSIX also shares sentences with these, for which no sentence is quoted: dengue (1 paper); heart failure (1); lung adenocarcinoma (1); Turner syndrome (1).